HNF1A (HNF1 homeobox A)
Diseases named in the same sentence as HNF1A in open-access papers (continued):
Sharing a sentence is not in itself a finding about the gene and the disease.
Hepatic steatosis (10 papers, 2012 to 2025). Steatosis is a term used to denote lipid accumulation within hepatocytes. "The mutations of HNF1α are well established in HCA characterized by hepatic steatosis due to increased fatty acid synthesis and decreased expression of liver fatty acid-binding protein (LFABP)." (PMID 34771521, 2021). "Conversely, if patients with fatty change of the liver of unknown origin are seen in childhood, HNF1A defects should be considered to be one of several causes of fatty liver." (PMID 22672869, 2012). "We utilized a targeted approach to modulate the expression of HNF1α and then evaluated hepatic steatosis in control and MASLD mice." (PMID 39910053, 2025). "Recent studies revealed HNF1α as a direct transcriptional repressor of PPARγ in the context of hepatic steatosis." (PMID 32235813, 2020). "However, to our knowledge, there have been no reports of liver steatosis in young children who have the HNF1A mutation." (PMID 22672869, 2012).
prostate carcinoma (10 papers, 2018 to 2026). A carcinoma that arises from epithelial cells of the prostate gland. "We have uncovered that aberrant upregulation of GI master regulators HNF4G and HNF1A alters enhancer landscape and chromatin accessibility conducive to the expression of GI-specific transcriptome in prostate cancer cells." (PMID 40553565, 2025). "Our result in a prostate cancer cell line further confirmed the role of HNF1A in regulating ACE2." (PMID 35012625, 2022). "The gastrointestinal gene signature was orchestrated by the transcription factors HNFG4 and HNF1A; the induction of HNFG4 and HNF1A-mediated pathway is required to sustain the proliferation of SPINK1-overexpressing prostate cancer cells, independently of AR signaling." (PMID 31366128, 2019). "Interestingly, a recent study SPINK1-positive castrate resistant prostate cancer identified POU5F1/OCT4 as part of a gastrointestinal gene signature present in SPINK1-positive prostate cancer and regulated by HNF1A and its target gene HNF4G." (PMID 30074477, 2018). "HNF1A overexpression leads to increased ACE2 expression and HNF1A knockdown reduced ACE2 expression in LNCaP cells, a prostate cancer cell line." (PMID 35012625, 2022). "In the colon cfDNA pool, TFs EVX2, DLX2, HNF1A, HNF4A, and HNF4G and TFs AR and HOXB13 in the prostate cancer cfDNA pool had increased accessibilities, whereas FOXA1 exceeded the >5 z-score threshold in both the prostate and breast pool." (PMID 31604930, 2019). "Researchers found that HNF4G/HNF1A was highly expressed in prostate cancer, and that the lack of HNF4G/HNF1A inhibited the growth of prostate cancer cells." (PMID 34234870, 2021).
atherosclerosis (9 papers, 2010 to 2025). A disease characterized by the build-up of fatty material and calcium deposition in the arterial wall resulting in partial or complete occlusion of the arterial lumen. "Therefore, this variant may influence multiple atherosclerosis-related genes or their plasma products through effects on HNF-1α structure or function." (PMID 26209006, 2015). "Mechanically, increased 3‐MH facilitated atherosclerosis progression through NPC1L1‐mediated intestinal cholesterol absorption in a HNF1A‐dependent manner." (PMID 39949981, 2025). "HNF1A has a wide range of functions, but recent evidence suggests that it may serve as a link between metabolic and inflammatory pathways involved in atherosclerosis." (PMID 22937776, 2012). "As such it could be involved in the pathogenesis of atherosclerosis and further work is required to define the role of HNF-1α more exactly." (PMID 21062467, 2010). "Besides, the fact that HNF1A polymorphism has been linked with susceptibility to both CAD and its important risk traits points to some pleiotropic actions of the gene on disease pathways leading to atherosclerosis." (PMID 25057215, 2014). "We can speculate that HNF1A may play a role in the regulation of sCD36; however, further study with a larger population size is required to confirm its potential use as a marker of atherosclerosis." (PMID 24069322, 2013). "In addition, we evaluated the potential relationship between HNF1A rs1183910, LEPR rs4420065, GCKR rs1260326, NLRP3 rs12239046, IL1F10 rs6734238, PPP1R3B rs9987289, ASCL1 rs10745954, HNF4A rs1800961 and SALL1 rs10521222 polymorphisms and CV events or subclinical atherosclerosis in RA patients." (PMID 27534721, 2016). "Furthermore, since the majority of implicated variants were noncoding, we speculate that some other entities at this genomic locus, rather than the HNF1A gene per se, are likely to be the primary contributors to the disease pathways of atherosclerosis." (PMID 25057215, 2014).
colorectal cancer (9 papers, 2017 to 2025). A primary or metastatic malignant neoplasm that affects the colon or rectum. "Based on its oncogenic role in PDAC and preliminary evidence as a metastatic driver in colorectal cancer, we first aimed to establish a pro-metastatic function for HNF1A in PDAC." (PMID 40731412, 2025). "Studies in prostate, renal, and colorectal cancers further support an oncogenic function for HNF1A." (PMID 40731412, 2025). "However, the significance of HNF1A expression and its role in colorectal cancer are mostly unknown." (PMID 33990627, 2021). "Moreover, knockout of SREBP2 or HNF1α in colorectal cancer cells could not inhibit the expression of PCSK9 induced by methionine." (PMID 40125618, 2025).
Hypertension (9 papers, 2011 to 2025). The presence of chronic increased pressure in the systemic arterial system. "For instance, we found that the rs7305618 SNP near HNF1A was nominally associated with a family history of hypertension." (PMID 27366637, 2016). "Subsequently, we found one nominal association with a binary trait: rs7305618 (HNF1A) with family history of hypertension (odds-ratio = 1.389 [1.054–1.829], P = 0.02)." (PMID 27366637, 2016). "One nominally significant association was found: rs7305618 (HNF1A) with family history of hypertension (1.389 [1.054–1.829] P = 0.020)." (PMID 27366637, 2016). "Testing the associations of the HNF1A rs7305618 SNP with adult hypertension in independent studies may therefore be relevant." (PMID 27366637, 2016). "HNF1A mutation carriers display a distinct hypertension status." (PMID 27366637, 2016). "An interaction between HNF1A G319S and active cigarette smoking at baseline was significant on the outcome of 10-year changes in 2-hour postload glucose (p = 0.027) with adjustment for age, sex, hypertension, triglyceride, and waist circumference." (PMID 21208426, 2011). "An interaction between HNF1A G319S and active cigarette smoking at baseline was not statistically significant on the outcome of 10-year changes in fasting glucose (p = 0.13) with adjustment for age, sex, hypertension, triglyceride, and waist circumference." (PMID 21208426, 2011).
pancreatic ductal adenocarcinoma (8 papers, 2015 to 2026). An infiltrating adenocarcinoma that arises from the epithelial cells of the pancreas. "The locus encoding the transcription factor HNF1A harbors susceptibility variants for pancreatic ductal adenocarcinoma (PDAC), while KDM6A, encoding Lysine‐specific demethylase 6A, carries somatic mutations in PDAC." (PMID 32154941, 2020). "Pancreatic ductal adenocarcinoma (PDAC) subtyping typically relies on immunohistochemistry (IHC) staining for critical markers like HNF1A and KRT81, a labor‐intensive manual staining process that introduces variability." (PMID 41188199, 2026). "We previously identified an oncogenic role for the transcription factor HNF1A in pancreatic ductal adenocarcinoma (PDAC)." (PMID 40731412, 2025). "Earlier studies have reported a role for HNF1α in pancreatic ductal adenocarcinoma (PDAC) but it is controversial." (PMID 33214606, 2020). "For pancreatic ductal adenocarcinoma (PDAC), two IHC markers, hepatocyte nuclear factor‐1A (HNF1A) and cytokeratin‐81 (KRT81), have emerged as practical surrogates for defining relevant PDAC subgroups." (PMID 41188199, 2026).
gastric cancer (7 papers, 2013 to 2025). A primary or metastatic malignant neoplasm involving the stomach. "Functional enrichment of DEGs linked HNF-4α and HNF-1α genes as highly expressed in Cldn6high gastric cancer." (PMID 36430456, 2022). "HNF4A and the related HNF1A factor are the most up-regulated transcription factors of the network in the gastric cancer cohort, with a mean expression (normalized mRNA expression z score) of 0.711 and 0.866, respectively." (PMID 41425714, 2025). "In gastric cancer, HNF1A increased HCG18 expression and HCG18 promoted cancer progression through the miR-152-3p/DNAJB12 axis." (PMID 34991445, 2022). "The expression of MCL-1 in stomach is regulated by hypoxia-inducible factor 1 alpha (HNF1-α) in Helicobacter pylori-infected human gastric epithelium and HMGB1 in gastric cancer cells." (PMID 35221802, 2022). "Next, we analyzed the immunoreactivity of HNF1α among all cancers in the TCGA database and found that PDAC had the second highest immunoreactivity next only to stomach cancer." (PMID 33214606, 2020). "The family member ELF3 was well expressed in the mRNA level in a subset of gastric cancers (n = 91), and its expression correlated with the expression of other transcription factors involved in gastric cancer pathogenesis, including HNF4A, HNF1A, CDX2, GATA4, GATA6, and EHF." (PMID 41425714, 2025). "The other component comprises several circuits involving miR-17, miR-195 and miR-497 together with NF1 (a hypoxia-activated gene), TFAP4 (another cancer gene with prognostic importance in gastric carcinoma), MYC and HNF1A, and common target genes, which can mainly be classified as cancer genes." (PMID 23987127, 2013).
Hypercholesterolemia (7 papers, 2018 to 2025). An increased concentration of cholesterol in the blood. "HNF1α knockout mice also exhibit hepatomegaly and fatty liver, and homozygous Hnf1α deficiency in mice leads to hyperbileacidemia, hypercholesterolemia, and altered bile acid synthesis and uptake." (PMID 40149950, 2025). "Within the liver, Hnf1a orchestrates bile acid and plasma cholesterol metabolism in hepatocytes, as evidenced by the onset of hypercholesterolemia in Hnf1a-/- mice." (PMID 37137894, 2023). "Together, the results presented above, especially parallel expression of PCSK9 and HNF1α both in vivo and in vitro, suggest that up-regulation of HNF1α contributes to the increase in liver PCSK9 gene expression and leads to hypercholesterolemia in lipectomized rats." (PMID 30483910, 2019).
liver fibrosis (7 papers, 2017 to 2025). "Our data demonstrate decreased HNF-1α mRNA levels, which suggests the development of hepatic inflammation and liver fibrosis." (PMID 41614817, 2025). "In contrast, the activity of HNF4α and HNF1α, which are central regulators of hepatic differentiation and known to inhibit epithelial‐to‐mesenchymal transition in liver fibrosis, were significantly reduced." (PMID 39605182, 2025). "Prevention of lipid metabolism disorders by maintaining β-oxidation and preventing ER stress; Inhibition of HNF1A to regulate hepatic fibrosis." (PMID 36267567, 2022). "For instance, it showed hints of effectiveness in NAFLD and hepatic fibrosis models in which hepatic knockout of HNF-1α in rats notably worsen liver fibrosis, while re-expression helped alleviation." (PMID 31685031, 2019). "HNF4α and HNF1α expression is lost during liver fibrosis and HCC progression, while their exogenous expression triggers growth arrest in hepatoma cell lines and induces hepatocyte differentiation in dedifferentiated cells." (PMID 31543815, 2019). "Most significantly, HNF4α and HNF1α delivery in animal models attenuates liver fibrosis and inhibits growth of xenograft tumors." (PMID 31543815, 2019). "HMGB1 mediates p65/miR-146b signaling and inhibits HNF1A to regulate hepatic fibrosis." (PMID 36267567, 2022).
lung carcinoma (7 papers, 2012 to 2024). "Interestingly, PDA-associated HNF1A SNPs rs7310409, rs1169300, and rs2464196 are also associated with both an elevated risk (1.5–2 fold) of developing lung cancer and elevated circulating C-reactive protein (CRP)." (PMID 30074477, 2018). "HNF1A, ALX1, AR, and GR play certain roles in lung cancer development and progression, and/or they have been associated with the overall survival." (PMID 36832225, 2023).
breast carcinoma (6 papers, 2017 to 2024). "These include EMT (TWIST1, SNAIL1, RUNX1, RUNX2, HIF1, and NOTCH1), breast cancer maintenance (OCT4, SP1, GATA1, ATF1, FOXO3a, ELK1, VDR, and NRF1), pro-metastatic responses (SMAD2/3, HNF1a, GLI1, NANOG, YY1, MYB1, and AP1), and immune modulation (STAT1/3)." (PMID 38398186, 2024).
gestational diabetes (6 papers, 2022 to 2025). Carbohydrate intolerance first diagnosed during pregnancy. "Studies have shown that 38% of women with MODY3 (HNFIA) gene mutations have a history of gestational diabetes; HNF1A gene mutations are often seen in women with gestational diabetes, which shows that HNF1A plays an important role in the susceptibility to gestational diabetes." (PMID 35957821, 2022). "The diagnosis of HNF1A/HNF4A-MODY is considerably less prevalent among individuals with presumed gestational diabetes." (PMID 39902162, 2024).
insulinoma (6 papers, 2009 to 2023). "We have previously provided biological evidence in insulinoma cell lines and transgenic mice models of HNF1A-MODY, that beta cells undergoing apoptosis induce the expression of the PSP/reg gene in neighbouring beta cells." (PMID 22808921, 2012). "Overexpression of either HNF1α or HNF1β induces ACE2 mRNA levels in mouse pancreatic islet cells and rat insulinoma cells." (PMID 37608279, 2023). "Our predictions, for HNF1A and HNF1B factors, have been formerly reported experimentally to drive ACE2 expression in pancreatic islet cells and insulinoma cells, respectively." (PMID 33244381, 2020). "Two of our predictions, for HNF1A and HNF1B, have been previously identified experimentally to drive ACE2 expression in pancreatic islet cells and insulinoma cells, respectively." (PMID 33112891, 2020).
macrosomia (6 papers, 2021 to 2025). "The only observational study assessing the incidence of fetal macrosomia in women with HNF1A-MODY reported that it was significantly less frequent in HNF1A, as compared to GCK-MODY (10% vs. 31.2%, p = 0.01)." (PMID 40649834, 2025). "HNF4A- and HNF1A-MODY affected pregnancies require increased surveillance for foetal macrosomia in utero and neonatal hypoglycaemia soon after delivery." (PMID 38933924, 2024). "Heterozygous mutations in HNF4A were known to cause macrosomia but not with HNF1A." (PMID 39421536, 2024).
chronic kidney disease (5 papers, 2013 to 2023). Impairment of the renal function secondary to chronic kidney damage persisting for three or more months. "Herein, we found the coordinated overexpression of genes encoding RelA/p65 (a subunit of NF–κB) and HNF1α in the livers of chronic renal failure (CRF) rats—an experimental model of CKD." (PMID 36012158, 2022). "Recently, we have found upregulation of genes encoding HNF1α and HNF4α in the livers of rats with experimentally induced chronic renal failure (CRF)." (PMID 29330688, 2018). "Thus, the results presented here and reported previously suggest that HNF1α is a master transcription regulator of genes encoding for (a) fibrinogen (results presented herein), (b) proteins involved in lipid metabolism, and (c) proinflammatory proteins in chronic kidney disease." (PMID 36982805, 2023). "We recently determined that hepatocyte nuclear factor 1α (HNF1α) was upregulated in the livers of chronic renal failure (CRF) rats—experimental model of CKD." (PMID 29330688, 2018). "Our findings suggest that NF–κB could be a downstream component (element) of the HNF1α-initiated signaling pathway in liver of chronic renal failure rats." (PMID 36012158, 2022). "In the Polish cohort, we identified 3 HNF1A-MODY patients with chronic kidney disease (CKD) defined as CKD-EPI estimated GFR (eGFR) <60 ml/min/1.73 m2; there were 5 such individuals in the T1DM group, 6 in the T2DM group and none in the ND group." (PMID 22350134, 2013). "We identified 8 patients with chronic kidney disease (CKD) defined as CKD-EPI creatinine equation (eGRF-cr) <60 mL/min/1.73 m2; there were 5 such individuals in the T2DM group, 2 in HNF1A-MODY group, and 1 in T1DM group." (PMID 26347889, 2015).
Cirrhosis (5 papers, 2012 to 2026). A chronic disorder of the liver in which liver tissue becomes scarred and is partially replaced by regenerative nodules and fibrotic tissue resulting in loss of liver function. "The suggested expression changes in HNF4A and IL6 mRNA, but not HNF1A were validated in liver tissue of patients with cirrhosis as compared to nine controls without." (PMID 36652164, 2023). "It is known that in mice the hepatocyte-specific deletion of HNF1A leads to the spontaneous development of HCC due to fatty liver without cirrhosis." (PMID 35327967, 2022).
Glucose intolerance (5 papers, 2010 to 2025). Glucose intolerance (GI) can be defined as dysglycemia that comprises both prediabetes and diabetes. "Mutations in HNF1α are responsible for the commonest type of monogenic diabetes (MODY3), characterised by progressive glucose intolerance due to an insulin secretory defect." (PMID 29764441, 2018). "Of note, HNF4A regulates the expression of HNF1A and is therefore expected that, with the exception of normoglycemic glycosuria, the HNF4A-MODY phenotype is similar to that of HNF1A-MODY, with glucose intolerance becoming evident during adolescence or early adulthood and deteriorating with age." (PMID 35052457, 2022).
monogenic diabetes (5 papers, 2008 to 2022). "HNF1α, is an activator encoded by the most frequently mutated gene in human monogenic diabetes (MODY3)." (PMID 30212457, 2018). "This was carried out with primary β-cells and hepatocytes freshly isolated from mice lacking Hnf1α, an activator encoded by the most frequently mutated gene in human monogenic diabetes (MODY3)." (PMID 18497863, 2008).
ovarian carcinoma (5 papers, 2015 to 2025). A malignant neoplasm originating from the surface ovarian epithelium. "The function and relationships between ovarian cancer and other upregulated mRNA genes (PRKCA, HNF1A, and MAP2K5) are not clear and further investigation is necessary." (PMID 39592485, 2025).
Renal cyst (5 papers, 2009 to 2025). A fluid filled sac in the kidney. "Consistent with our previous results, hepatocyte nuclear factor family members HNF1α (z-score = −7.3) and HNF4α (z-score = −5), which regulate glucose homeostasis and tissue-specific gene expression, were again predicted to be highly inhibited and both were indeed downregulated in renal cysts." (PMID 39000280, 2024).
endothelial dysfunction (4 papers, 2019 to 2026). In vascular diseases, endothelial dysfunction is a systemic pathological state of the endothelium (the inner lining of blood vessels) and can be broadly defined as an imbalance between vasodilating and vasoconstricting substances produced by (or acting on) the endothelium. "Cumulatively, these changes could account for signs of endothelial dysfunction in HNF1A-MODY patients." (PMID 41749365, 2026).